SLC1A5 (solute carrier family 1 member 5)
Diseases named in the same sentence as SLC1A5 in open-access papers (continued):
Sharing a sentence is not in itself a finding about the gene and the disease.
ovarian carcinoma (continued). "circ_0025033 might promote ovarian cancer progression via hsa_miR-370-3p/SLC1A5, providing an interesting insight into ovarian cancer tumorigenesis." (PMID 36273140, 2022). "Mechanistically, circ_0025033 could regulate SLC1A5 expression in ovarian cancer cells via binding to hsa_miR-370-3p." (PMID 36273140, 2022). "As the proteins HRNPM and SLC1A5 are associated with the cell cycle regulators p21 or p27, the apoptosis regulators PTEN and PUMA, and the VEGF-R2 it is concluded that both proteins have role in the pathogenesis of ovarian cancer." (PMID 28609484, 2017). "In parallel, SLC1A5 might abolish the anti-ovarian cancer role of hsa_miR-370-3p." (PMID 36273140, 2022). "Furthermore, SLC1A5 protein expression was notably enhanced in ovarian cancer tissue and cells." (PMID 36273140, 2022). "Furthermore, SLC1A5 upregulation could abrogate hsa_miR-370-3p-triggered anti-ovarian cancer." (PMID 36273140, 2022). "We found that claudin-4 forms an axis with the amino acid transporters SLC1A5 and LAT1 to regulate autophagy, facilitating the elimination of a product of genome instability, micronuclei, thus preventing the accumulation of genomic instability in ovarian cancer." (PMID 38867360, 2024). "As the proteins HRNPM and SLC1A5 are related to the cell cycle regulators p21 or p27, the apoptosis regulators PTEN or PUMA, and the angiogenesis regulator VEGF-R2 it might be concluded, that both have a functional role in the pathogenesis of epithelial ovarian cancer." (PMID 28609484, 2017).
colon cancer (17 papers, 2014 to 2025). "SLC7A5 was the most consistently up-regulated gene in the Trp pathway in cultured colon cancer cell lines, and Western blots confirmed that SLC7A5 protein was dramatically up-regulated in colon cancer cells, while changes in SLC1A5 were more modest." (PMID 31416966, 2019). "Surprisingly, only one colon cancer cell line displayed an increase in SLC1A5 when compared with HCECs." (PMID 31416966, 2019). "Silencing SLC1A5 or SLC7A5 in the colon cancer cell line HCT15 led to a reduction of 13C-Trp and 13C-Kyn observed 1 h after addition of 13C-Trp to the culture medium." (PMID 31416966, 2019). "Interestingly, TCGA analysis demonstrated that most colon cancer samples have greater expression of the tryptophan transporters SLC1A5 and SLC7A5 and the enzyme AFMID than the normal tissues from the same patients." (PMID 31922097, 2020). "We found that MYC promotes the import of tryptophan into colon cancer cells by transcriptionally driving the expression of SLC7A5 and SLC1A5, which are capable of transporting tryptophan." (PMID 31922097, 2020). "To validate these results, we performed RT-qPCR for SLC1A5, SLC7A5, TPH1, TDO2, IDO1, AHR, and MYC in colon cancer and normal tissue of the same patients." (PMID 31416966, 2019). "Our results confirmed that SLC7A5, SLC1A5, TDO2, IDO1, and AHR were all elevated in colon cancer, while TPH1 was reduced." (PMID 31416966, 2019). "SLC7A5, SLC1A5, and AFMID were elevated in colon cancer cells and tissues, and kynurenine was significantly greater in tumor samples than in the respective adjacent normal tissue from patients with colon cancer." (PMID 31416966, 2019). "Indeed, previous immunohistochemistry (IHC) studies found that both SLC1A5 and SLC7A5 were up-regulated in colon cancer cells." (PMID 31416966, 2019). "Elevated levels of the enzymes TDO2, IDO1, and AFMID combined with the Trp transporters SLC1A5 and SLC7A5 in colon cancer patients may lead to increased Trp and Kyn levels in colon cancer cells." (PMID 31416966, 2019).
neuroblastoma (17 papers, 2015 to 2025). Neuroblastoma (NB) is the most common solid, extracranial childhood tumor. "4-(18F)Fluoro-Gln uptake in neuroblastoma cells is mainly mediated by SLC1A5, and overexpression of SLC1A5 is associated with poor clinical prognosis." (PMID 33401748, 2021). "It was also reported that MYCN-amplified neuroblastoma cells rely on the amino acid transporter ASCT2 (solute carrier family 1 member 5, SLC1A5) for the provision of glutamine, in which its expression correlates with poor patient survival." (PMID 37414143, 2023). "For instance, robust MYCN binding was mapped across the SLC1A5 (ASCT2) locus, which encodes a known regulator of glutamine metabolism, a key feature of neuroblastoma tumorigenesis." (PMID 37835497, 2023). "Studies in neuroblastoma cell lines also found high expression of SLC1A5 and confirmed that Na+-dependent glutamine uptake accounted for more than 95% of the total glutamine uptake in this cell." (PMID 35874898, 2022). "Subsequent investigation revealed that MYCN-amplified neuroblastoma cells express high levels of ASCT2 (also known as SLC1A5), which functions as a major transporter for uptake of glutamine in MYCN-amplified neuroblastoma cells." (PMID 36077650, 2022). "We next repeated the TDP-43 IP-qPCR assays in the nuclear extracts of SH-SY5Y neuroblastoma cells treated with MPP+ in triplicate and found that TDP-43 binding to MALAT1 was significantly increased, while TDP-43 binding to the 3′ UTR of SLC1A5, CSNK1E, and HMGB2 mRNAs was significantly decreased." (PMID 39837396, 2025).
leukemia (16 papers, 2016 to 2025). A malignant (clonal) hematologic disorder, involving hematopoietic stem cells and characterized by the presence of primitive or atypical myeloid or lymphoid cells in the bone marrow and the blood. "On the contrary, Slc1a5 deletion causes a reduction in AML development in mouse models of leukemia induced by the overexpression of MLL-AF9 oncogene or following Pten deletion." (PMID 34445444, 2021). "Mechanistically, the loss of Slc1a5 induces a global effect on metabolism, reducing leucine influx and mTOR signaling and ultimately leading to apoptosis in leukemia cells." (PMID 34445444, 2021). "In leukemia, elevated expression of SLC1A5 facilitates glutamine uptake, a necessary process for the synthesis of glutathione and pyrimidine to drive chemo-resistance in the leukemic blast cells." (PMID 38539506, 2024). "Pharmacological inhibition of SLC1A5, using GPNA or ASCT2 knockout, reduced leukemia progression in PDX models." (PMID 40756330, 2024). "In xenograft models, GPNA can reduce the development and progression of leukemia driven by MLL-AF9 or PTEN deficiency, suggesting that SLC1A5 is a promising therapeutic target for the treatment of leukemia." (PMID 37249801, 2023). "In a mouse model of leukemia, targeting SLC1A5 reduced the intracellular glutamine content and hindered the activation of mTORC1, which interfered with the energy supply, leading to the inhibition of cell growth and cell cycle progression." (PMID 37249801, 2023). "Such a compensatory mechanism has been described in HL-60 leukemia cells which show increased expression of the glutamine transporter, the glycoprotein SLC1A5, after induction of hypoglycosylation by TM." (PMID 35603178, 2022). "The STAT3–MYC axis promotes the survival of leukemia stem cells by regulating SLC1A5 and oxidative phosphorylation." (PMID 36275721, 2022). "We found that ASCT2/SLC1A5, a major glutamine transporter, was indeed deglycosylated upon glucose deprivation and 2-deoxyglucose exposure in HL-60 and K-562 leukemia cells." (PMID 27344174, 2016). "In addition, lower expression of SLC1A5 was observed in breast, esophagus, leukemia, lung, and sarcoma tumors in some datasets." (PMID 34367941, 2021). "Maria LA and colleagues found that STAT3 mediated oxidative phosphorylation in leukemia stem cells (LSCs) by regulating MYC expression and thus modulate the transcription of SLC1A5 that was involved in glutamine metabolism and TCA cycle." (PMID 37249801, 2023). "Research has shown that by inhibiting IGF2BP2, CWI1-2 can regulate the expression of key targets (such as MYC, GPT2, and SLC1A5) in the glutamine metabolism pathway in an m6A-dependent manner, thereby inhibiting the development of AML and the self-renewal of leukemia stem cells." (PMID 38790013, 2024). "IGF2BP2, by targeting genes involved in glutamine (Gln) metabolism, such as Glutamic–Pyruvic Transaminase 2 (GPT2), Solute Carrier Family 1 Member 5 (SLC1A5), and MYC, supports the self-renewal of leukemia stem cells and progenitor cells, thereby facilitating AML progression." (PMID 39342406, 2024). "In recent work, a non-specific inhibitor of glutamine transporter SLC1A5, namely L-c-glutamyl-p-nitroanilide (GPNA), showed efficacy in inhibiting leukemia progression in a xenograft AML model in vivo." (PMID 38539506, 2024).
acute myeloid leukemia (13 papers, 2017 to 2026). Acute myeloid leukemia (AML) is a group of neoplasms arising from precursor cells committed to the myeloid cell-line differentiation. "IGF2BP also stabilizes MYC, GPT2, and SLC1A5 mRNA to promote acute myeloid leukemia (AML) development." (PMID 41041073, 2025). "IGF2BP2 recruits proteins such as eIF4E and eIF3A to MYC, GPT2, and SLC1A5 mRNA, regulating glutamine metabolism in acute myeloid leukemia and modulating the immune response of macrophages through epigenetic reprogramming." (PMID 39726589, 2024). "Moreover, the STAT3–MYC axis regulates the neutral amino acid transporter SLC1A5, controlling the influx of glutamine into acute myeloid leukemia cells, maintaining their energy metabolism and survival." (PMID 39534558, 2024). "Studies have shown that STAT3 regulates MYC expression in acute myeloid leukemia (AML), thereby controlling SLC1A5 transcription and OXPHOS and promoting the survival of leukemia stem cells." (PMID 36902385, 2023). "In acute myeloid leukemia (AML), IMP2 stabilizes key mRNAs, including MYC, GPT2, and SLC1A5, that are essential for glutamine uptake and metabolism, fueling the TCA cycle and supporting AML cell proliferation and survival." (PMID 40141058, 2025).
head and neck squamous cell carcinoma (12 papers, 2018 to 2025). A squamous cell carcinoma that arises from any of the following anatomic sites: lip and oral cavity, nasal cavity, paranasal sinuses, pharynx, larynx, and salivary glands. "Zhanget al. reported that SLC1A5-dependent glutamine uptake is critical for the tumorigenesis of head and neck squamous cell carcinoma." (PMID 35593463, 2022). "Other studies have shown that ASCT2 (SLC1A5), a glutamine transporter, is an EGFR-associated protein in EGFR-overexpressing human head and neck squamous cell carcinoma (HNSCC)." (PMID 34805266, 2021). "In head and neck squamous cell carcinoma (HNSCC) cells, SLC7A11 expression contributes to resistance to oxidative stress, and high expression of SLC7A11 and SLC1A5 is correlated with the dedifferentiation status of cancer cells." (PMID 35011702, 2022). "Additionally, paracrine CCL2 from F. nucleatum-reprogrammed adipocytes upregulates SLC1A5 and SLC7A11 in head and neck squamous cell carcinoma (HNSCC), leading to glutathione (GSH) accumulation and cisplatin resistance." (PMID 41276817, 2025).
esophageal cancer (10 papers, 2019 to 2025). A primary or metastatic malignant neoplasm involving the esophagus. "SLC1A5 silencing was reported to inhibit oesophageal cancer growth by inducing cell cycle arrest and apoptosis." (PMID 37894450, 2023). "Previous studies have shown that circSFMBT2 drove aggressive esophageal carcinoma phenotypes through the miR-107 dependence modulation for SLC1A5." (PMID 35874898, 2022). "Esophageal cancer growth was suppressed by SLC1A5 silencing via cell cycle arrest and apoptosis." (PMID 31409775, 2019).
lymph node metastasis (9 papers, 2017 to 2025). "Patients exhibiting high PSAT1 and SLC1A5 expression were more likely to develop lymph node metastasis, while high PHGDH, PSPH and SLC1A5 expression were associated with distant metastasis." (PMID 40660426, 2025). "Higher expression levels of SLC1A5 or MTHFD2 were associated with poorer OS and relapse-free survival (RFS), advanced tumor stages, and increased likelihood of lymph node metastasis in KIRC patients." (PMID 39958609, 2024). "In addition, SLC1A5 overexpression was found to be a separate prognostic factor when assessed only for lymph node metastasis." (PMID 37829798, 2023). "In thyroid cancer, SLC1A5 is reported to be expressed in only tumor cells and related to the BRAF V600E mutation, which is associated with extrathyroidal extension, advanced TNM stage, lymph node metastasis, multifocality and recurrence." (PMID 31409775, 2019). "Our study also demonstrated that higher expression of SLC1A5 in GC tissues was significantly correlated with worse clinicopathologic features, such as deeper local invasion, more lymph node metastasis, advanced TNM stages and higher Ki-67 expression, which indicated poor prognosis." (PMID 29100325, 2017). "SLC1A5 expression level was not related to clinical stage, lymph node metastasis, or overall survival rate of tumors." (PMID 39223142, 2024).
clear cell renal cell carcinoma (8 papers, 2015 to 2025). "The aim of this study was to assess the clinical significance of SLC1A5 in patients with clear-cell renal cell carcinoma (ccRCC)." (PMID 26599282, 2015). "In clear cell renal cell carcinoma (ccRCC), comprehensive analysis of m6A-seq and mRNA-seq analysis identified the glutamine transporter SLC1A5 as an FTO target, and the FTO-SLC1A5 axis is crucial for the metabolic reprogramming and survival of ccRCC cells." (PMID 37192910, 2023).
thyroid cancer (8 papers, 2019 to 2025). "Further analysis revealed that SLC1A5 has been shown to be a target gene of miR-199a-5p in thyroid cancer." (PMID 41317550, 2025). "To elucidate the mechanism of STAG2-deficient thyroid cancer cells being more sensitive to glutamine deprivation, we first determined the impact of STAG2 knockdown on the expression of glutamine transporter SLC1A5 and glutaminases GLS and GLS2, which are essential for glutamine metabolism." (PMID 37479689, 2023). "Thus, we first detected SLC1A5 expression in thyroid cancer and normal tissues." (PMID 31409775, 2019). "This is also the case for thyroid cancers; several amino acid transporters such as SLC7A5 (LAT1), SLC1A5 (ASCT2) and SLC7A11 (xCT) are overexpressed in thyroid cancer tissues, with some of them correlating with patients’ poor prognosis." (PMID 36557253, 2022). "Other glutamine metabolism-related genes, such as solute carrier family 1 neutral amino acid transporter member 5 (SLC1A5, also known as ASCT2), phosphoserine aminotransferase 1 (PAST1), GPT, and glutamic-oxaloacetic transaminase (GOT), were also highly expressed in thyroid cancer cells." (PMID 38386265, 2024).
Obesity (7 papers, 2016 to 2025). Accumulation of substantial excess body fat. "In the study, the decreased expression of PPARγ in obese WAT trans-activates the uptake transporter Slc1a5; impaired PPARγ in obesity leads to the downregulation of SLC1A5 and decreased adipocyte uptake of glutamine and methionine (two epigenetic modulators), which disrupts Bmal1." (PMID 37626963, 2023). "We thus wondered whether PPAR-γ plays a role in obesity-repression of SLC1A5." (PMID 35198059, 2022). "SLC1A5 (ASCT2) deficits in intestinal epithelial cells impair antimicrobial peptide synthesis, worsening inflammatory bowel disease (IBD), while reduced expression in psoriasis and obesity disrupts skin and T cell function." (PMID 41425581, 2025).
osteosarcoma (7 papers, 2017 to 2022). A usually aggressive malignant bone-forming mesenchymal neoplasm, predominantly affecting adolescents and young adults. "As proof, ASCT2 (SLC1A5) knockdown in osteosarcoma and cervical cancer cells can induce upregulation of SNAT1 (SLC38A1)." (PMID 33511116, 2020). "RNA-seq data from the Cancer Cell Line Encyclopedia (CCLE; Broad Institute) indicated relatively low-baseline mRNA expression of the serine transporter ASCT2/SLC1A5, which could explain why PHGDH inhibition cannot be compensated for with extracellular serine and glycine in osteosarcoma cells." (PMID 33503424, 2021). "However, in some tumor cell lines, such as 143B osteosarcoma cells, loss of SLC1A5 did not suppress tumor growth, but instead elicit an amino acid starvation response and up-regulation of SLC38A1, indicating that SLC38A1 may act as a rescue transporter when SLC1A5 is blocked." (PMID 36262284, 2022).
metastatic tumors (6 papers, 2017 to 2025). "Several Gln transporters were shown to regulate tumor cell growth and were associated with PCa progression to castration-resistant and metastatic disease, including ASCT2 (SLC1A5), LAT1 (SLC7A5), and LAT2 (SLC7A8)." (PMID 39199642, 2024). "The expressions of both cystine transporters (SLC7A11, SLC3A2) and cysteine transporters (SLC1A4, SLC1A5) were significantly upregulated in CRC compared with paired non-tumor tissues, but were similar in primary tumors and metastatic tumors." (PMID 39079386, 2024).
endometrial cancer (5 papers, 2017 to 2024). Primary or metastatic malignant neoplasm involving the endometrium (mucous membrane that lines the endometrial cavity). "Inhibition of SLC1A5 glutamine transport by small molecules and shRNA-mediated SLC1A5 knockdown have been shown to decrease endometrial cancer cell growth." (PMID 31580259, 2019).
esophageal squamous cell carcinoma (5 papers, 2017 to 2026). Esophageal squamous cell carcinoma (ESCC) is a type of esophageal carcinoma (EC) that can affect any part of the esophagus, but is usually located in the upper or middle third. "Studies have shown that NEDD4L inhibits esophageal squamous cell carcinoma by inducing MYC ubiquitination and decreasing SLC1A5 expression." (PMID 41561975, 2025).
lung adenocarcinoma (5 papers, 2019 to 2025). A carcinoma that arises from the lung and is characterized by the presence of malignant glandular epithelial cells. "The SLC1A5-mediated delivery of the PGS/siRNA complex was shown in cisplatin-resistant human lung adenocarcinoma A549/DDP cells significantly overexpressing SLC1A5." (PMID 36839686, 2023). "The protein expression of SLC3A2, SLC11A2, SLC1A5, SLC16A1, SLC39A7, SLC39A14 in the lung adenocarcinoma cell line A-549 and H1299 is higher than that in the normal lung epithelial cell line Beas-2B." (PMID 37973895, 2023). "The gene expression of SLC3A2, SLC16A1, SLC39A14, SLC39A7, SLC1A5, and SLC11A2 in the lung adenocarcinoma cell line A-549 and H1299 is higher than that in the normal lung epithelial cell line Beas-2B." (PMID 37973895, 2023). "Furthermore, SLC1A5 protein expression was significantly higher in lung adenocarcinomas with lymph node metastasis compared to node negative tumors, as well as increased in adenocarcinomas with higher pTNM staging." (PMID 35223460, 2021).
viral infection (5 papers, 2017 to 2025). "Thereby, SLC1A5 stands out due to its involvement in other viral infections." (PMID 40667466, 2025).